SNORA67 (small nucleolar RNA, H/ACA box 67)
Synonyms: U67; RNU67
Gene: Small nucleolar RNA gene on chromosome 17 (7,577,955 to 7,578,091, forward strand). Ensembl gene ENSG00000277985.
Gene Ontology:
Biological process: RNA processing
Cellular component: nucleolus
Homologues: Orthologues: chimpanzee SNORA67 (100% identical), macaque SNORA67 (96% identical), guinea pig SNORA67 (85% identical), mouse Gm24029 (77% identical), rat Snora67 (77% identical).
Diseases named in the same sentence as SNORA67 in open-access papers:
SNORA67 is named in the same sentence as 2 diseases in open-access papers, as found by Europe PMC text mining. Sharing a sentence is not in itself a finding about the gene and the disease. The quoted sentences say what the papers report.
breast carcinoma (1 paper, 2022). "Another study reported a similar connection between the elevated expression of DKC1 with upregulated expression of SNORA67 and increased U1445 modification on 18S ribosomal RNA in a breast cancer cell line." (PMID 35719370, 2022).
tumor (1 paper, 2019). "Interestingly, two H/ACA snoRNAs, SNORA24 and SNORA67, identified in our expression analysis upon RASG12V-induced senescence, were significantly decreased in HCC specimens compared to matched adjacent non-tumor tissue (p<1.35×10−9 and p<4.6×10−7, respectively)." (PMID 31478838, 2019).